TENT5A (terminal nucleotidyltransferase 5A)
Description:
Cytoplasmic non-canonical poly(A) RNA polymerase that catalyzes the transfer of one adenosine molecule from an ATP to an mRNA poly(A) tail bearing a 3'-OH terminal group and participates in the cytoplasmic polyadenylation. Polyadenylates mRNA encoding extracellular matrix constituents and other genes crucial for bone mineralization and during osteoblast mineralization, mainly focuses on ER-targeted mRNAs (By similarity).
Synonyms: C6orf37; FAM46A; XTP11; FLJ20037; OI18
Tractability: PROTAC: ubiquitination databases record sites on it.
Gene: Protein-coding gene on chromosome 6 (81,491,439 to 81,752,774, reverse strand). Ensembl gene ENSG00000112773.
Subcellular location: Cytoplasm
Subcellular location (Human Protein Atlas): Nucleoplasm; Cytosol
Gene Ontology:
Molecular function: poly(A) RNA polymerase activity; protein binding; RNA binding
Biological process: mRNA stabilization; positive regulation of bone mineralization; positive regulation of osteoblast differentiation; regulation of ossification
Cellular component: cytoplasm
Genetic constraint (gnomAD): Loss-of-function variants: 9 observed, 28.83 expected, observed/expected ratio (o/e) 0.31, 90% interval 0.19 to 0.55. The upper end of that interval is the gene's LOEUF score, 0.55, which puts it in group 2 of 6, group 1 being the genes least tolerant of losing a copy. Missense variants: 408 observed, 594.83 expected, observed/expected ratio (o/e) 0.69, 90% interval 0.63 to 0.74. Synonymous variants: 262 observed, 247.79 expected, observed/expected ratio (o/e) 1.06, 90% interval 0.95 to 1.17.
Homologues: Orthologues: chimpanzee TENT5A (100% identical), macaque TENT5A (99% identical), pig TENT5A (96% identical), dog TENT5A (95% identical), guinea pig TENT5A (95% identical), rabbit TENT5A (94% identical), mouse Tent5a (93% identical), rat Tent5a (93% identical), tropical clawed frog tent5a (82% identical), zebrafish tent5aa (75% identical), zebrafish tent5ab (73% identical), Drosophila melanogaster CG46385 (53% identical), and 6 more. Paralogues in human: TENT5C (64% identical), TENT5B (58% identical), TENT5D (53% identical).
Diseases named in the same sentence as TENT5A in open-access papers:
TENT5A is named in the same sentence as 32 diseases in open-access papers, as found by Europe PMC text mining. Sharing a sentence is not in itself a finding about the gene and the disease. The quoted sentences say what the papers report.
adolescent idiopathic scoliosis (4 papers, 2022 to 2025). A scoliosis with no known cause arising in adolescent. "Elsewhere in the body, TENT5A exon 2 VNTRs are associated with skeletal conditions such as osteoarthritis of hip and knee and adolescent idiopathic scoliosis, an assignment made reasonable by the strong expression of TENT5A in human and murine osteoblasts." (PMID 39127989, 2024). "TENT5A also impacts the formation of muscle fibers in adolescent idiopathic scoliosis by preserving production of myogenin." (PMID 37239396, 2023). "Paravertebral muscle asymmetry may be involved in the pathogenesis of adolescent idiopathic scoliosis (AIS), and the Tent5a protein was recently identified as a novel active noncanonical poly(A) polymerase." (PMID 35137485, 2022).
retinal diseases (3 papers, 2018 to 2024). "TENT5A was first described as C6orf37 (Chromosome 6 open reading frame 37), a protein of unknown function with possible relation to human retinal diseases including retinitis pigmentosa." (PMID 30397099, 2018).
leukemia (2 papers, 2020 to 2026). A malignant (clonal) hematologic disorder, involving hematopoietic stem cells and characterized by the presence of primitive or atypical myeloid or lymphoid cells in the bone marrow and the blood. "Furthermore, our results also suggest that in leukemia cells, TENT4A, TENT5A, TENT5B, TENT5C, TENT5D, and TUT1 may mediate the non-templated nucleotide additions to the 3'ends of miRNAs." (PMID 42038404, 2026).
Obesity (2 papers, 2020 to 2026). Accumulation of substantial excess body fat. "Our data identify a role of Tent5a in enhancing insulin production, which may be involved in boosting insulin synthesis and maintaining euglycemia in obesity." (PMID 42161934, 2026).
osteogenesis imperfecta (2 papers, 2022 to 2023). Osteogenesis imperfecta (OI) comprises a heterogeneous group of genetic disorders characterized by increased bone fragility, low bone mass, and susceptibility to bone fractures with variable severity. "Patients identified with mutation of Tent5a were associated with severe osteogenesis imperfecta, and skeletal dysplasia was found in the mouse with Tent5a mutation." (PMID 35137485, 2022).
atherosclerosis (1 paper, 2023). A disease characterized by the build-up of fatty material and calcium deposition in the arterial wall resulting in partial or complete occlusion of the arterial lumen.
COVID-19 (1 paper, 2025). A disease caused by infection with severe acute respiratory syndrome coronavirus 2. "Thus, we immunized wild-type and Tent5a−/− mice with mRNA-1273, BNT162b2 or a Nuvaxovid (Novavax) protein-based COVID-19 vaccine, and measured antibody production (14 days after vaccination)." (PMID 40240603, 2025). "In vivo, TENT5A enhances the immunogenicity of the anti-COVID-19 mRNA-based vaccines mRNA-1273 and BNT162b2, but not that of Nuvaxovid, which contains purified spike protein as an antigen." (PMID 40240603, 2025).
Infertility (1 paper, 2024). "Despite the partial infertility associated with Tent5a KO, the morphology of male sperm and testis was normal." (PMID 38909026, 2024).
scoliosis (1 paper, 2025). A congenital or acquired spinal deformity characterized by lateral curvature of the spine. "Inhibiting Tent5a expression can reduce myoblast proliferation, migration, and differentiation, and also inhibit the maturation of type I muscle fibers, leading to decreased muscle asymmetry, improved spinal stress balance, and reduced scoliosis progression." (PMID 41181183, 2025).
TENT5A also shares sentences with these, for which no sentence is quoted: glioma (5 papers); non-small cell lung carcinoma (3); osteoarthritis (3); cancer (2); lung cancer (2); ovarian carcinoma (2); prostate carcinoma (2); retinitis pigmentosa (2); tuberculosis (2); tumor (2); breast carcinoma (1); colorectal cancer (1); infection (1); Insulin resistance (1); major depression (1); male infertility (1); metabolic disease (1); osteogenesis imperfecta, type 18 (1); osteoporosis (1); posterior cortical atrophy (1); pulmonary tuberculosis (1); skeletal dysplasia (1); Stuve-Wiedemann syndrome (1).